FBN1 (fibrillin 1)
Diseases named in the same sentence as FBN1 in open-access papers (continued):
Sharing a sentence is not in itself a finding about the gene and the disease.
Marfan syndrome (continued). "Notably, in Marfan syndrome, PEx is considered a clinical manifestation of the inherited fibrillin-1 deficiency." (PMID 39596629, 2024). "There has been long‐standing debate about whether FBN1 variants cause Marfan syndrome through HI, DN mechanisms, or both." (PMID 39219382, 2024). "For instance, for FBN1, the gene mutated in Marfan syndrome and included 1621 pathogenic mutations." (PMID 38185709, 2024). "The rise in blood pressure, together with a pre-diseased aortic wall due to the Fibrillin-1 mutation in patients with Marfan syndrome could explain the earlier occurrence of AADA." (PMID 39201043, 2024). "Marfan syndrome (MFS) is classically caused by a pathogenic fibrillin-1 (FBN1) variant." (PMID 38379908, 2024). "However, studies of Marfan Syndrome (a connective tissue disorder due to mutations in Fibrillin-1/FBN) indicated that neonatal administration of BAPN caused accelerated dilation of the ascending aorta and even premature death in Marfan Syndrome mice." (PMID 38183136, 2024). "Marfan syndrome is caused by pathogenic variants in the fibrillin 1 gene (FBN1)." (PMID 39830211, 2024). "Marfan syndrome (MS) is a pleiotropic connective tissue disorder with variable expressivity inherited as an autosomal dominant trait and is caused in most cases by a mutation in the FBN1 gene located on chromosome 15q21.1, encoding fibrillin-1." (PMID 39456956, 2024). "In humans, deregulated TGF-β signaling caused by the mutations of TGFΒR2, TGFΒ2, TGFΒ3, SMAD2, SMAD3, and FBN-1 is associated with Loeys-Dietz syndrome or Marfan syndrome, both of which are characterized by various skeletal anomalies such as long bone overgrowth." (PMID 38267638, 2024). "Marfan syndrome (MFS) is a syndromic disease caused by mutations in the gene encoding fibrillin-1." (PMID 38177536, 2024). "Fibrillin-1 haploinsufficiency causes Marfan syndrome in approximately 10%–15% of patients." (PMID 39830211, 2024). "Marfan syndrome (MS) is an autosomal dominant inheritance of connective tissue disease with an estimated incidence of 1 in 5000; and in 90% of cases, it is caused by mutations in the gene for fibrillin-1, the main component of extracellular microfibrils." (PMID 38198071, 2024). "Specific FBN1 gene variants are known to cause Marfan syndrome." (PMID 38399505, 2024). "Marfan syndrome (MFS) results from pathogenic mutations in the fibrillin-1 gene." (PMID 39049903, 2024). "While the FBN1 gene mutation is tied to Marfan syndrome, its association with skeletal muscle microfibrils suggests that rare variants in AIS patients could lead to vertebral and muscular structural changes due to altered elasticity." (PMID 38137689, 2023). "Additionally, evidence of variants in the FBN1 gene and its correlation to intrinsic myocardial dysfunction and Marfan syndrome (MFS) is significantly growing." (PMID 37270590, 2023). "The third scenario was of Marfan syndrome which is caused by a mutation in a gene called FBN1." (PMID 37692649, 2023). "This involves both canonical (SMAD2/3) and non-canonical downstream signaling pathways, as demonstrated by several knockout mouse models of MMVD, including the Fbn-1 (fibrillin-1; Marfan syndrome), FLN-A (filamin-A X-linked), and Fstl1 (follistatin) mouse models." (PMID 37908840, 2023). "For example, gene mutation causing systemic diseases such as Marfan syndrome (FBN1), Ehlers-Danlos syndrome (COL3A1), and Loeys-Dietz syndrome (TGFBR1/2) could significantly increase the risk of aortic dissection." (PMID 37596272, 2023). "The FBN1 gene is essential for the production of fibrillin, and its mutation could cause Marfan syndrome." (PMID 37441579, 2023). "Different pathogenic variants of the FBN1 gene are associated with Marfan syndrome and lead to a decreased amount of FBN1 available to form microfibrils, which function as a skeleton for elastin deposition and control the direction of growth for elastic fibres." (PMID 36670346, 2023).
Marfan syndrome (continued). "Recent preclinical models in a mouse model of Marfan syndrome have shown that variation in the FBN-1 gene is associated with excessive activation of transforming growth factor-beta (TGFβ), which in turn contributes to the phenotypic expression of MFS, including SV dilation." (PMID 37160466, 2023). "The first was a variant in FBN1, a gene known to be associated with Marfan syndrome." (PMID 37946251, 2023). "Finally, we provided evidence of FBN1 involvement in IVD function by showing that lumbar IVDs in patients with Marfan syndrome, caused by heterozygous FBN1 gene mutation, were significantly more degenerated." (PMID 36966180, 2023). "The FBN1-associated diseases include Marfan syndrome and skin stiffness syndrome." (PMID 36118693, 2022). "The FBN1/2 genes encode fibrillin, a glycoprotein of the extracellular matrix, and mutations in these genes have been reported in a variety of fibrillin-related disorders (i.e., Marfan syndrome)." (PMID 35682604, 2022). "Marfan syndrome is characterised by a tendency to develop predominantly aortic diseases (aneurysms and dissections) and special skeletal and ocular features, which are mainly caused by FBN1 gene mutations." (PMID 36295040, 2022). "Marfan syndrome is inherited in an autosomal dominant pattern and is characterized by a number of clinical features, with the majority of patients having mutations in the fibrillin-1 (FBN1) gene, which codes for the glycoprotein fibrillin-1." (PMID 36337905, 2022). "FBN1 (fibrillin 1), a significant paralog of this gene, has mutations linked to Marfan syndrome." (PMID 36453946, 2022). "For example, similar to the patient with the likely pathogenic FBN1 variant, the patient with the potentially pathogenic variant had features consistent with Marfan syndrome (e.g., joint subluxations, double-jointedness, tall stature, long arms and thin body habitus)." (PMID 35918752, 2022). "FBN1 was first recorded as an associated gene with Marfan syndrome (MFS)." (PMID 35307021, 2022). "First, the existence of increased circulating TGF-β1 activity and concentration in other connective tissue disorders such as heterotopic ossification, characterized by ectopic bone formation in extraskeletal tissues and Marfan syndrome, caused by mutations in fibrillin-1, an ECM protein." (PMID 35223854, 2022). "Marfan syndrome is caused by pathogenic variants of the gene encoding fibrillin-1 and may present with abnormalities in the cardiovascular, skeletal, ocular, pulmonary, integumentary, and central nervous systems." (PMID 35741851, 2022). "Marfan Syndrome (MFS) is a systemic disorder caused by mutations in fibrillin-1." (PMID 35055593, 2022). "Given that FBN1 variant status is a marker of the certainty of a diagnosis of Marfan syndrome, this finding is what might be expected if an ARB is effective at slowing root expansion in this condition." (PMID 36049495, 2022). "Marfan syndrome (MFS) is a rare inherited disorder of the connective tissue with an autosomal dominant mode of inheritance which happens as a result of a mutation in the fibrillin-1 (FBN1) gene located on chromosome 15q21.1." (PMID 36340521, 2022). "Heterozygous FBN1 mutations cause the connective tissue disorder Marfan syndrome." (PMID 34698377, 2022). "In addition, FBN1 was found associated with two other musculoskeletal diseases, systemic sclerosis and Marfan syndrome." (PMID 35606786, 2022). "Moreover, children with Marfan syndrome having variant c.5187G>A p.(Trp1729*) of gene FBN1 can have a rare presentation with cerebral arteritis or intracerebral bleed." (PMID 36262952, 2022). "In one patient, concomitant Marfan syndrome was confirmed for having positive family history, carrying a heterozygous known disease-causing mutation in FBN1 gene (c.7240C > T/p.Arg2414Ter), and presence of typical features (rachnodactyly, ventrical septal defect, and mitral valve regurgitation)." (PMID 34122512, 2021).
Marfan syndrome (continued). "We obtained a molecular diagnosis in 45/53 (85%) index patients, in which 36/53 (68%) had rare variants in FBN1 (Marfan syndrome; 63 patients in total), seven (13.3%) in TGFBR1/TGFBR2 (Loeys–Dietz syndrome; nine patients in total) and two patients (3.7%) in SKI (Shprintzen–Goldberg syndrome)." (PMID 33436942, 2021). "Moreover, patients diagnosed with connective tissue disorders such as Marfan’s syndrome commonly display scoliosis and rare variants in the Marfan’s associated fibrillin genes FBN1/2 are associated with AIS in humans." (PMID 34318745, 2021). "Corrected the pathogenic mutation FBN1 (T7498C) of Marfan syndrome in HEK293T cells and in heterozygous human embryos using the BE system, showing an overall correction rate of 89% and no detection of off-target, insertions/deletions (indels) in intended sites." (PMID 34805315, 2021). "Given the presence of fibrillin-1 microfibers in the myocardium, myocardial dysfunction and associated arrhythmia are conceivable and have been shown to contribute to morbidity and mortality in patients with Marfan syndrome." (PMID 34336739, 2021). "Additionally, we identified a linkage group of high-frequency variants (MAFs ~10%) encompassing FBN1, the causal gene for Marfan syndrome, which was associated with TAA." (PMID 34469433, 2021). "Thus, with Marfan syndrome, caused by mutations in the FBN1 gene encoding fibrillin-1, there is a decrease in the level of extracellular fibrillin-rich microfibrils, which usually act as a reservoir for TGF-β." (PMID 34945243, 2021). "Mutations in the fibrillin genes cause alterations in elastogenesis and connective tissue disorder conditions, such as Marfan syndrome or Weill-Marchesani syndrome if mutations occur in the FBN1 gene, or congenital contractural arachnodactyly (Beals syndrome) if the FBN2 gene is altered." (PMID 34945227, 2021). "For instance, mutations in FBN1 (fibrillin-1), the causal gene for Marfan syndrome, may increase the risk of thoracic aortic aneurysms or dissections even in individuals who do not have Marfan syndrome." (PMID 34469433, 2021). "In addition to Marfan syndrome caused by FBN1 mutations, many studies have also reported that abnormal FBN1 expression is related to tumor malignant phenotype, including ovarian cancer and papillary thyroid carcinoma." (PMID 34407841, 2021). "Marfan syndrome is one of the most common dominantly inherited connective tissue disorders, affecting 2–3 in 10,000 individuals, and is caused by one of over 2800 unique FBN1 mutations." (PMID 33801742, 2021). "Similarly, rs589668 in FBN1 was associated with an increase in body height and blood pressure, and a reduced body fat percentage as observed in Marfan syndrome." (PMID 33226994, 2020). "The mutation in the FBN1 associated with the classic type of Marfan syndrome." (PMID 31918677, 2020). "Compound heterozygous mutations in FBN1 were identified in a large family with Marfan syndrome." (PMID 31950671, 2020). "Allelic truncating mutations of FBN1 could cause either classical Marfan syndrome (MFS) or a more complicated phenotype associated with Marfanoid–progeroid–lipodystrophy syndrome (MPLS)." (PMID 31774634, 2020). "Marfan syndrome (MS) is a primary disorder of connective tissue with diagnostic criteria centered around cardiovascular, musculoskeletal, and ocular phenotypes linked to a single gene FBN1 which encodes an extracellular matrix protein." (PMID 33226994, 2020). "Marfan syndrome is the result of a mutation in FBN1, the gene encoding the fibrillin-1 protein." (PMID 32998474, 2020). "Marfan syndrome (MFS) is a dominant monogenic disorder caused by mutations in FBN1." (PMID 31950671, 2020). "This study showed that FBN1 gene frameshift and nonsense mutations are more common in patients with aortic dissection and may have meaningful guidance for the treatment of Marfan syndrome patients." (PMID 31830381, 2020).
Marfan syndrome (continued). "Therefore, the expression level of FBN1, which is transcribed and translated into a functional fibrillin protein, is associated with disease onset and the severity of Marfan syndrome." (PMID 32210272, 2020). "Pathogenic FBN1 variants resulting in defective fibrillin-1 cause Marfan syndrome (MFS)." (PMID 32987703, 2020). "FBN1 encodes fibrillin 1, a key structural component of the extracellular matrix, and its variants are associated with a wide range of hereditary connective tissues disorders, such as Marfan syndrome (MFS) and mitral valve–aorta–skeleton–skin (MASS) syndrome." (PMID 31185693, 2019). "Patients with Marfan syndrome exhibit craniofacial defects of the hard palate, as well as an abnormally tall stature with long limbs and long thin fingers, due to mutations in the fibrillin-1 (FBN1) gene on chromosome 15." (PMID 30463190, 2018). "Homozygous MgR mice show the 72% of reduction in Fbn1 (encoding mouse fibrillin-1) expression because of transcriptional interference by insertion of the PGKneo-cassette and resemble the phenotype of Marfan syndrome by showing 10% longer long bones than wild-type (WT) littermates." (PMID 30585249, 2018). "Marfan syndrome is almost exclusively inherited in an autosomal dominant manner with most patients harboring mutations involving the gene (FBN1) encoding the connective tissue protein fibrillin-1." (PMID 30455800, 2018). "Marfan syndrome (MS) is a multisystem disorder caused by a mutation in FBN1 gene." (PMID 30151001, 2018). "Another explanation is that the non-Marfan syndrome patients may also have mutation in FBN1 gene or other gene resulted in longer AL." (PMID 28673264, 2017). "Marfan syndrome is known to be associated with mutations in the fibrillin 1 (FBN1) gene." (PMID 28529940, 2017). "An example of the importance of the biomechanical strength conferred by MBs is evident in ciliary zonules, where an abundance of fibrillin-1 microfibrils is responsible for holding the lens in dynamic suspension, with a loss of this structural anchorage in Marfan syndrome leading to ectopia lentis." (PMID 28315339, 2017). "The other lesson is that variants in or near a single gene lead to a spectrum of severity and manifestations of AAD, akin to pleiotropy; a notable example is FBN1 variants, for which clinical phenotype can range from severe forms of Marfan syndrome to merely an increased risk of AAD in adulthood." (PMID 28993736, 2017). "Mutations in FBN1 may be associated with depleted or abnormal adipose tissue, seen in some patients with Marfan syndrome and lipodystrophies." (PMID 27386756, 2016). "Marfan syndrome is caused by mutations in the fibrillin-1 gene (FBN1)." (PMID 28050285, 2016). "This includes mutations in human fibrillin 1, which is mutated in Marfan syndrome." (PMID 25798732, 2015). "For example, because Marfan Syndrome is caused by mutation of the fibrillin-1 gene, it is tempting to speculate that smPPARγOE-induced reductions in fibrillin-1 contribute to the structural alterations in the vascular wall." (PMID 26451838, 2015). "To address this, we assessed the effect of two major classes of CCB in a mouse line heterozygous for a cysteine substitution in an epidermal growth factor-like domain in fibrillin-1 (Fbn1C1039G/+), representative of the most common class of mutations causing Marfan syndrome." (PMID 26506064, 2015). "Asp-492 is in one of the conserved EGF-like domains and may be involved in Ca2+ binding and/or growth factor binding to Fbn1, which is essential for the elastic fiber formation in aortic tissue, and mutations to which cause Marfan syndrome." (PMID 25689165, 2015). "Mutations in the fibrillin-1 gene FBN-1 may cause aberrant fibrillin microfibril assembly and hence the profound aortic pathologies which characterize Marfan syndrome." (PMID 25014552, 2014). "Most patients with Marfan syndrome were shown to have a mutation in the fibrillin-1 (FBN1) gene." (PMID 24720641, 2014).
Marfan syndrome (continued). "For instance, neonatal Marfan syndrome or specific mutations in the FBN1 gene may be more severe than other forms of Marfan syndrome, e.g. a manifestation of ectopia lentis and skeletal abnormalities." (PMID 24954169, 2014). "Two new variants, including one nonsense SNP in the Marfan syndrome gene FBN1 and one missense mutation in exon 15 of LRP1, which may be related to the phenotype of the patients were identified." (PMID 24484584, 2014). "Defect of FBN1 has been considered to be the cause of Marfan syndrome since 1991." (PMID 24484584, 2014). "Marfan syndrome, an autosomal dominant heritable disorder, results from mutations in the FBN1 gene, which encodes fibrillin-1, an extracellular matrix component found in micro-fibril structures characterized by wide variety of skeletal, ocular, and cardiovascular anomalies." (PMID 25551100, 2014). "Finally, we included 4 patients with a causative FBN1 mutation who remained below current diagnostic thresholds for the final diagnosis of Marfan syndrome." (PMID 24349050, 2013). "Marfan syndrome with causative FBN1 mutations is associated with an increased risk for arrhythmia, and affected persons may require life-long monitoring." (PMID 24349050, 2013). "Defective fibrillin-1 may cause Marfan syndrome phenotype by disrupting the structure of the connective tissue elastic fibres." (PMID 24349050, 2013). "Our finding of lower maximal heart rates and prolonged PQ- and QTc intervals in PVC>10/h and in Couplet/nsVT is also described in clinically diagnosed Marfan syndrome, where primary tissue defects due to FBN1 gene mutations may be causative." (PMID 24349050, 2013). "Baseline characteristics of 80 patients with Marfan syndrome and FBN1 mutation." (PMID 24349050, 2013). "Interestingly, both Marfan syndrome (caused by FBN1 mutations) and familial TAA caused by ACTA2 mutations are associated with aortic valve malformation." (PMID 22970404, 2012). "FBN1 mutations cause Marfan syndrome, whose major cardiovascular complication is sporadic TAAD." (PMID 23450299, 2012). "With the technology, one group created a human Marfan syndrome "model" to prove the hypothesis that fibrillin-1 mutations result in the disease phenotypes." (PMID 22512921, 2012). "In a second example of “genetic hitchhiking,” the SLC24A5 allele was positively selected in Europeans for the effect of decreasing freckles, but this allele also caries several rare, linked, deleterious mutations in FBN1, several of which have been shown to cause Marfan's syndrome." (PMID 23300552, 2012). "Our data adds a novel mutation to the spectrum of FBN1 gene mutations, analyzes the potential functional consequence of the mutation, and enriches the existing knowledge of genotype–phenotype correlations of Marfan syndrome." (PMID 21976953, 2011). "Marfan syndrome is classically caused by mutations in the fibrillin 1 (FBN1) gene." (PMID 21527992, 2011). "In addition, among the 7 potential mutations in 6 disease-causing genes, two novel mutations were identified in two genes (STS and FBN1), which are involved in X-linked ichthyosis disease and Marfan syndrome, respectively." (PMID 22216297, 2011). "Interestingly, mutations in FBN1, which is a member of the fibrillin family, are associated with the Marfan syndrome." (PMID 21777459, 2011). "MFAP1 is located near FBN1 and mutations in both genes are causal for Marfan syndrome." (PMID 20949002, 2010). "However, the identification of other cattle with a mutation in the FBN1 gene established that arachnomelia is phenotypically distinct from Marfan syndrome." (PMID 20865119, 2010). "A dominant negative effect of FBN1 mutations has been the leading hypothesis for the pathogenesis of Marfan syndrome for a long time." (PMID 20886638, 2010).